PARP1 (poly(ADP-ribose) polymerase 1)
Diseases named in the same sentence as PARP1 in open-access papers (continued):
Sharing a sentence is not in itself a finding about the gene and the disease.
prostate carcinoma (continued). "It has been described in prostate cancer stem cells, and with an enhanced effect when trabectedin is administered in combination with other drugs like PARP1 inhibitors in sarcoma or campthotecin in sarcoma models." (PMID 38396735, 2024). "Poly(ADP-ribose) polymerase 1 (PARP-1) plays a central role in controlling androgen receptor function in prostate cancer cells." (PMID 38731869, 2024). "In prostate cancer, functional inactivation of PARP-1 upregulates TGF-β levels and Smads, thereby inducing EMT and promoting tumorigenesis in vivo." (PMID 39201718, 2024). "PARP-1 is one of the most abundantly expressed nuclear proteins and is found to be overexpressed in the prostate cancer." (PMID 36834491, 2023). "In this study, we are reporting the preclinical evaluation of an Auger-emitting radio-brominated PARP-1 inhibitor, [77Br]Br-WC-DZ, in prostate cancer cell lines and in vivo models." (PMID 36834491, 2023). "Our TMA analysis corroborated the previous studies that PARP-1 expression is higher in prostate cancer than in normal prostate tissues." (PMID 36834491, 2023). "Among these RBPs, PARP1 was selected as the potential downstream target, for which PARP1 participates in the progression of castration‐resistant prostate cancer." (PMID 36597139, 2023). "We analyzed the correlation between PARP-1 expression and Gleason score in a prostate cancer tissue microarray." (PMID 36834491, 2023). "Several recent studies demonstrated the clinical benefit of targeting PARP-1 with Olaparib in advanced prostate cancer harboring defects in DNA repair." (PMID 37215708, 2023). "Poly (ADP-ribose) polymerase-1 (PARP-1) is a chromatin-binding DNA repair enzyme overexpressed in prostate cancer." (PMID 36834491, 2023). "Overall, this study, for the first time, provides evidence that a PARP-1-targeting Auger emitter can offer antitumor effects in in vivo prostate cancer models with minimal toxicity." (PMID 36834491, 2023). "In vitro invasion assays showed that PARP-1 inhibition attenuates Erg- and Etv1-dependent invasion in prostatic cancer cell lines." (PMID 37686260, 2023). "In the current study, our approach is to target PARP-1 in prostate cancer cells with a PARP-1 inhibitor (WC-DZ-Br) labeled with the Auger emitter bromine-77 ([77Br]Br-WC-DZ)." (PMID 36834491, 2023). "The present study aims to continue investigating the potential mechanism of action of corchorusoside C in a zebrafish model and in DU-145 prostate cancer cells to further evaluate its effects on the expression of PARP-1 and NF-κB pathway elements." (PMID 36498874, 2022). "We have evaluated the utility of a PARP-1 tracer to delineate responses to targeted alpha particle radiotherapy in a mouse model of prostate cancer." (PMID 35906379, 2022). "We then performed studies to define the biology of GZ17-6.02 and the PARP1 inhibitor olaparib alone and in combination in prostate cancer cells." (PMID 36408163, 2022). "Limitations of this study include the evaluation of a high PARP-1 expressing prostate cancer cell model, and the use of immunohistochemistry to evaluate changes in expression." (PMID 35906379, 2022). "PARP inhibitors are approved in breast, ovarian, pancreatic, and prostate cancers harbouring a pathogenic variant in BRCA1 or BRCA2, where PARP1 inhibition results mainly in synthetic lethality in cells with impaired homologous recombination." (PMID 35681784, 2022). "Preclinical studies of prostate cancer demonstrate that PARP1 enzymatic activity is enhanced and required for AR function, tumour cell growth, and progression to castration resistance." (PMID 36497408, 2022). "The present studies demonstrated that GZ17-6.02 interacted with the PARP1 inhibitor olaparib to kill prostate cancer cells." (PMID 36408163, 2022). "A mechanistic study was pursued in a zebrafish model and in DU-145 prostate cancer cells to investigate the selectivity of 1 towards NF-κB and PARP-1 pathway elements." (PMID 36498874, 2022).
prostate carcinoma (continued). "Olaparib is inhibiting PARP1, PARP2, and PARP3 and is used as a therapy for cancer in people with hereditary BRCA1 or BRCA2 mutations, which include some ovarian, breast and prostate cancers." (PMID 33481867, 2021). "Piperine has other effects in inhibition of prostate cancer cells, such as it can result in cleavage of PARP-1." (PMID 35069196, 2021). "All these results are indicative of the selectivity of guanine scaffold in anticancer drug development, especially as PARP1 inhibitors in breast, ovarian and prostate cancer." (PMID 34376738, 2021). "The results suggest that compounds can be developed as chemotherapeutic agents, specifically as PARP1 inhibitors in breast, ovarian and prostate cancer." (PMID 34376738, 2021). "PARP1 is overexpressed in several types of cancer such as ovarian, breast, oral, and prostate cancer." (PMID 33809749, 2021). "PARP-1 overexpression in prostate cancer tissue compared with normal prostate suggests a greater activity of PARP-1 in these tumors." (PMID 32850156, 2020). "In conclusion, we have utilized an integrated strategy which combines cell‐free, cellular, and in silico assays for reducing a library of 664 small molecules to 9 unique PARP‐1 inhibitors for further development in the treatment of prostate cancer." (PMID 32342655, 2020). "The PARP-1 inhibitors are now approved for ovarian, breast, and prostate cancer with specific genomic alterations." (PMID 33158305, 2020). "Several PARP-1 inhibitors have been available on market for the treatment of breast, ovarian and prostatic cancer." (PMID 32779949, 2020). "PARP-1 has also been involved in prostate cancer progression, as PARP-1 expression in the nuclear matrix increases with tumor invasiveness." (PMID 31877876, 2019). "PARP1 expression is significantly up-regulated in several cancers including breast and ovarian cancer, although up-regulation is less striking in prostate cancer." (PMID 31357527, 2019). "LncRNA PlncRNA-1 was upregulated in prostate cancer samples and cell lines, so it can work as an inhibitor of apoptosis through promoting the cleavage of PARP-1, a key component of the DNA damage response." (PMID 31205469, 2019). "Increased PARP1 activity correlates also with more advanced disease and poor outcome in prostate cancer." (PMID 31357527, 2019). "PARP1 inhibition diminished AR activity and sensitized prostate cancer cells to both DNA damage and androgen depletion." (PMID 31404966, 2019). "Other recent studies support a relevant role of PARP-1/PARP-2 in prostate cancer biology, not only related to the well-described functions in DNA damage repair, but also as regularors of transcription factors." (PMID 31366128, 2019). "The data from clinical trials has shown that inhibiting the DNA repair enzyme PARP-1 in ovarian, breast, and prostate cancers improves outcome in patients that have genetic alterations in other components of the DNA repair machinery." (PMID 30305041, 2018). "There were also other studies that demonstrated the overexpression of PARP1 in prostate carcinoma, colorectal carcinoma, pediatric central nervous system carcinomas, and testicular germ cell tumors, respectively." (PMID 28991194, 2017). "PARP1 plays an integral role in DNA repair, in addition, a recent report showed that PARP1 was recruited to AR binding regions and promoted AR function in advanced prostate cancer." (PMID 28264478, 2017). "The striking difference was autoantibody responses to PARP1 in prostate cancer were very low percentage." (PMID 25865228, 2015). "There also seems to be a correlation between prostate cancer progression and PARP1 enzymatic activity, because this activity is enhanced on advanced prostate cancers." (PMID 24243533, 2014). "In a recent report, it was shown that PARP1 has protumorigenic effects on positive-AR prostate cancer cells." (PMID 24243533, 2014).
prostate carcinoma (continued). "Further studies revealed that piperine treatment resulted in the activation of caspase-3 and cleavage of PARP-1 proteins in LNCaP, PC-3 and DU-145 prostate cancer cells." (PMID 23824300, 2013). "We then investigated the possibility that cell necrosis mediated by the inhibition of PARP-1 concomitant with Ets-1 accumulation was due to an increase in DNA damage as observed with Ets fusion proteins in prostate cancer and Ewing's sarcoma." (PMID 23405229, 2013). "mtDNA depletion also reduces PARP-1 levels, which promotes progression of the neoplastic phenotype in prostate cancer." (PMID 24086362, 2013). "Recently, hyperactivation of poly (ADP-ribose) polymerase-1 (PARP-1) has been suggested to play an important role in β-lap-induced radiosensitization in prostate cancer cells that overexpress NQO1." (PMID 21998736, 2011). "Indeed, PARP1/2 inhibitors such as olaparib have been clinically used for treating solid tumors, including ovarian, breast, and prostate cancers." (PMID 41310943, 2026). "As prostate cancer becomes more aggressive, it may accumulate DNA repair defects or genomic instability, increasing reliance on PARP1." (PMID 40682676, 2026). "In prostate cancer radiosensitization research, the application of functional ex vivo assays enabled, for the first time, the direct observation of PARP1-dependent end joining (PARP1-EJ) repair switching in patient tumor samples." (PMID 41367875, 2025). "Additionally, functional assays such as the PARP1-EJ repair switch test in prostate cancer offer a direct way to assess tumor sensitivity to PARPis, enabling more individualized treatment." (PMID 41367875, 2025). "Interestingly, the mean expression was higher than in other cancer types, including cancers where the utilization of PARP1 inhibitors was approved or under clinical evaluation, including ovarian, breast, pancreatic, and prostate cancers." (PMID 38704604, 2024). "The implication of PARP-1 has also been demonstrated in prostate cancer progression." (PMID 39201718, 2024). "The reliance on PARP1 indicates the benefit BCL2-expressing prostate cancer patients may experience through PARPi therapies." (PMID 37508568, 2023). "circTFDP2 promotes prostate cancer progression via directly binding to PARP1." (PMID 36597139, 2023). "Our studies establish the fact that PARP-1 targeting Auger emitters could have therapeutic implications in advanced prostate cancer and provides a strong rationale for future clinical investigation." (PMID 36834491, 2023). "Thus, PARPi exploits the dual function of PARP1 in DNA damage repair and AR regulation to suppress multiple pathways critical for prostate cancer cell survival and progression." (PMID 37810962, 2023). "Moreover, EWS-FLI1 and EWS-ERG directly interact with PARP-1 and DNA-PKcs, blocking DNA repair in Ewing sarcoma and prostate cancer." (PMID 37686260, 2023). "Radio-brominated Auger emitting PARP-1 inhibitor [77Br]Br-WC-DZ could have the potential for clinical translation in advanced prostate cancer and warrants further investigation." (PMID 36834491, 2023). "We defined the biology of GZ17-6.02 in prostate cancer cells and determined whether it interacted with the PARP1 inhibitor olaparib to enhance tumor cell killing." (PMID 36408163, 2022). "In prostate cancer and kidney cancer, PARP1 is closely related to the metastasis of tumor cells." (PMID 36566215, 2022). "The role of PARP1 in triggering DNA repair processes in tumor development is well known, as well as its upregulation in various cancers; indeed, two of our studies demonstrated that the PARP1 protein was overexpressed in both prostate cancer and glioblastoma multiforme nuclei." (PMID 35741059, 2022). "Targetable prostate cancer mutations have been lacking, but PARP-1 inhibition has been effective in certain patients." (PMID 34359640, 2021). "Indeed, transient down regulation of RECQ4 blocks cell growth and induces PARP1-dependent apoptosis in metastatic prostate cancer cells." (PMID 34869606, 2021).
prostate carcinoma (continued). "Interestingly, and fittingly so, recent mechanistic evidence revealed that the silencing of PARP1 in prostate cancer cells suppresses their growth and induces MET." (PMID 33672595, 2021). "Blockade of AR function leads to reduced expression of several HR-associated genes such as BRCA1, RAD54L and RMI2, so that sequential treatment of a prostate cancer xenograft with the AR antagonist, enzalutamide, and the PARP-1 inhibitor, olaparib, strongly suppresses tumor growth." (PMID 33158305, 2020). "A recent study shows that Trop2 induces neuroendocrine phenotype of prostate cancer, and overexpression of Trop2 leads to the significant increase in Poly(ADP-Ribose) polymerase 1 (PARP1), an enzyme critical for DNA repair regulation, replication, transcription, and chromatin remodeling." (PMID 33187148, 2020). "A recent study in small cell lung cancer identified a link between EMT and resistance to PARP inhibitors in that disease setting and PARP-1 has been shown to regulate EMT in prostate cancer models through regulation of TGFβ signalling and changes in levels of ZEB1." (PMID 31080552, 2019). "As shown from the figure, PARP1 (cluster 1) was found to have conditional essentiality with cell lines having mutation in CHEK2 (cluster 3) and a survival advantage of down regulation of PARP1 in prostate cancer patients when CHEK2 was mutated." (PMID 31709193, 2019). "The role of PARP1 in regulating AR function in prostate cancer and the potential synergy between PARPi and AR signaling inhibitor was tested in another phase II randomized, double-blind study comparing olaparib and abiraterone versus placebo and abiraterone in mCRPC." (PMID 31404966, 2019). "As PARP1 inhibitors are used in clinical therapy of breast, ovarian and prostate cancer, and clinical trials are ongoing to analyze their efficacy in melanoma, colorectal, pancreatic and gastric cancer, we analyzed how somatic mutations of our candidate genes are distributed among these cancers." (PMID 31105872, 2019). "Moreover, flow cytometry with a specific antibody for Cleaved PARP-1, an apoptosis marker, confirmed the activation of apoptosis in leptin-exposed LNCaP line of prostate cancer cells." (PMID 31671654, 2019). "Interestingly, 9 out of 12 genes showed a medium expression correlation with PARP1 in prostate cancer; INCENP showed the highest correlation (p > 0.6)." (PMID 31105872, 2019). "We believe that our paper could be helpful for implementation of BRCA testing, particularly considering the increasing use for the assessment of PARP-1 sensitivity in other cancer entities, such as pancreatic and prostate cancers." (PMID 31600986, 2019). "Finally, it has been shown that treating prostate cancer xenografts with inhibitors to AR (bicalutimide) and PARP-1 (Olaparib) inhibits tumor growth." (PMID 30305041, 2018). "Strikingly, we found that OLAR5 cells had strongly down-regulated PARP1 protein expression, further suggesting that PARP1 protein is required for the toxicity of PARPi in EWSCs and consistent with sensitivity observed in prostate cancer and chicken DT40 cells where PARP trapping is operative." (PMID 26505995, 2015). "It is intriguing to note that knockdown of PARP1 poly (ADP-ribose) polymerase 1 (PARP1) in ERG-positive prostate cancer PC3 and DU145 cells may resensitize radioresistant cancer cells." (PMID 24739220, 2014). "Furthermore, PARP1 activity is required for tumor cell growth in vivo and its targeting potently suppresses tumor cell proliferation, suggesting that PARP1 can be targeted on human prostate cancer to suppress tumor growth." (PMID 24243533, 2014). "In prostate cancer, it was shown that AR can promote DNA repair through homologous recombination as its inhibition can mimic the loss-of-function of the breast cancer type 1 susceptibility protein (BRCA1) and confer cancer sensitivity to poly(ADP-ribose) polymerase 1 (PARP1) inhibitors." (PMID 40150035, 2025).
prostate carcinoma (continued). "That raises the question as to whether and how PARP-1 inhibition therapy can be extended to advanced prostate cancer patients lacking BRCA1/2 mutations." (PMID 36834491, 2023). "Thus, PARP-1 represents an important target in multiple cancer types, including prostate cancer." (PMID 37415740, 2023). "PARP1‐siRNA could inhibit the growth and invasion capacity of prostate cancer cell." (PMID 37491836, 2023). "This study evaluates whether PARP-1, on account of its proximity to the cell’s DNA, would be a good target for delivering high-linear energy transfer Auger radiation to induce lethal DNA damage in prostate cancer cells." (PMID 36834491, 2023). "Thus, the PARP1-E2F-1 complex may exhibit protooncogene functions, which was demonstrated in prostate cancer cells." (PMID 33572647, 2021). "In prostate cancer, MYCN enhances tumor progression by transcriptionally activating genes such as PARP1 and BRCA1." (PMID 40593489, 2025). "We have previously reported the utility of PARP-1 radioligands, specifically [18F]WC-DZ-F, for PET imaging in the prostate cancer." (PMID 36834491, 2023). "Treatment of the prostate cancer cell lines with the PARP-1 inhibitor 1,5-dihydroisoquinoline blocked RAR antagonist provoked necroptosis of prostate cancer cell line cells." (PMID 36768694, 2023). "PARP1, NQO1, HSPA5, and TOP1 were identified as potential molecular targets for ETV4-fusion-positive prostate cancer, and olaparib, amrubicin, fluorouracil, and irinotecan were suggested as candidate drugs, respectively." (PMID 36289913, 2022). "Here, we used a third-generation PARP1-specific radiotracer, [18F]-PARPZ, to delineate castrate resistant prostate cancer xenografts." (PMID 35906379, 2022). "PARP-1 is a druggable target in cancer for patients with BRCA deletions, including for prostate cancer patients." (PMID 35906379, 2022). "The PARP1 inhibitors olaparib and rucaparib are FDA approved for prostate cancer patients who present with advanced castration-resistant disease with homologous recombination repair deficits." (PMID 36408163, 2022). "The present studies were designed to investigate the biology of GZ17-6.02 in prostate cancer cells, and to define its interaction with the FDA-approved Poly ADP-ribosyl Polymerase 1 (PARP1) therapeutic olaparib." (PMID 36408163, 2022). "Interaction between ETV1, EWS-ERG fusion genes, and EWS-FLI1 fusion genes, members of ETS family transcription factors, and PARP1, a PARPBP-interacting partner has been demonstrated in Ewing sarcoma and prostate cancers." (PMID 35181635, 2022). "Following recent additional approvals, PARP1/PARP2 inhibitors are currently used against breast, ovarian, pancreatic, and prostate cancers." (PMID 34210965, 2021). "Of note, because of their critical role in the DDR, PARP1 and PARP2 have emerged as important anticancer drug targets, with several PARP inhibitors now used against breast, ovarian, pancreatic and prostate cancers in the clinic." (PMID 34116477, 2021). "Furthermore, it has been reported that PARP-1, which is involved in the mechanism of radiation induced DNA damage repair, is increased in the mesenchymal phenotype, and it could reduce the cell killing effects of RT in prostate cancer." (PMID 32290335, 2020). "A transcriptional role for MYCN in upregulating the DDR has been given further credence by the recent identification of MYCN binding sites in the promoters of PARP1, PARP2, BRCA1, RMI2, and TOPBP1, albeit in castration resistant prostate cancer." (PMID 32577161, 2020). "Preclinical studies showed that PARP1 can interact with ERG, and inhibition of PARP1 enhanced DNA double-strand breaks induced by ERG overexpression and slowed the growth of ERG-positive prostate cancer cells." (PMID 31404966, 2019). "Recently, a report detailing the strong interaction between PARP-1 and AR has generated much excitement over the potential for PARP inhibitors in prostate cancer treatment." (PMID 24350055, 2013).